GLI1 (GLI family zinc finger 1)
Diseases named in the same sentence as GLI1 in open-access papers (continued):
Sharing a sentence is not in itself a finding about the gene and the disease.
tumor (continued). "The lack of a defined, quantitative standard biomarker of the activated HH pathway, coupled with the broader role of GLI1 in tumours, means that the number and diversity of HH pathway tumours has been vastly overestimated." (PMID 30068568, 2018). "Consistently, about 50% of GLI1 transcripts are edited in human normal tissues, including cerebellum, skin, pancreas, ovary, and colon; on the other hand, in the corresponding tumors and tumor cell lines, the extent of GLI1 editing is reduced." (PMID 30098229, 2018). "A major strength of our study is that we compared the levels of individual Hh pathway components (SHH, PTCH1, and GLI1) in primary tumours with tumour adjacent normal epithelium." (PMID 30379908, 2018). "Significant correlation was observed between SHH (R.E = 12.76 ± 5.12, p < 0.0001), DHH (R.E = 9.8 ± 5.1, p < 0.05) and GLI1 (R.E = 12.3 ± 3.9, p < 0.0001) and invasive tumour size." (PMID 29329585, 2018). "As expected, compared to mice engrafted with control lentiviruses, mice engrafted with wild-type SuFu showed a reduced tumour growth rate, a reduced tumour volume (at the end point of the experiment), and a decreased Ki67 and Gli1 labelling." (PMID 29515120, 2018). "Pearson χ2 test analysis showed that expression level of Gli1 is correlated to the depth of tumor invasion (P < 0.001), lymph node metastasis (P = 0.021) and TNM staging (P = 0.003)." (PMID 29321573, 2018). "ERMS tumours from Ptch1+/− mice display high levels of some HH pathway target genes, including Gli1, Ptch1 and Igf2." (PMID 30068568, 2018). "These tumours arise as a consequence of loss of SNF5, a chromatin remodelling component, which can directly bind to GLI1." (PMID 30068568, 2018). "A significant correlation of SHH, DHH and GLI1 expression with advanced tumour size, stages, grades, nodal involvement and distant metastasis was observed (p < 0.05)." (PMID 29329585, 2018). "RNA editing of GLI1 has been detected in fetal and adult brain, lung, colon, pancreas and ovary tissues, while, on the contrary, in corresponding tumor cell lines the extent of editing was significantly decreased." (PMID 30158435, 2018). "In western blot analysis, 91.7% (22/24) and 87.5% (21/24) of tumor samples showed higher Gli1 and Gli2 expression than in paired normal tissue, respectively." (PMID 29416661, 2018). "SHH, DHH, PTCH1 and GLI1 were significantly over-expressed in tumours as compared with respective normal mammary tissues." (PMID 29329585, 2018). "Gli1 activation promoted TNBC progression and regulated VEGF signaling leading to tumor vascularization, while pharmacological inhibition of Smo counteracted the effects of Gli1 on tumor angiogenesis." (PMID 30248941, 2018). "We found that lower expression level of USP37 obviously impaired the expression of Hh targets (Smo and Gli-1) and cell proliferation marker Ki-67 in the tumor tissues as seen by immunohistochemical staining." (PMID 30482232, 2018). "Over-expression of SHH, DHH and GLI1 was significantly correlated with advanced stages and tumour grades of the cohort." (PMID 29329585, 2018). "It was recently demonstrated that selectively inhibiting HDAC1 and HDAC2 chemically decreases the tumor growth of SHH-MB in a murine model by inhibiting the Hedgehog pathway (Hh), which is further linked to an increase in GLI1 acetylation." (PMID 29099739, 2017). "While non- aggressive human BCC subtypes display high NEO1 expression, aggressive human BCC subtypes present with lower levels of NEO1, similar to GLI1, suggesting a possible role of SHH/GLI/NEO1 signaling in tumor aggressiveness." (PMID 29137400, 2017). "A significant longer survival period was also observed for mice with tumours derived from Caov3 SHH-OE cells co-injected with CAFs Gli1-shRNA compared to that of mice with tumours derived from Caov3 SHH-OE cells co-injected with CAFs shNC." (PMID 28978035, 2017).
tumor (continued). "In our results, the decline of Gli1 led to significant reduction of tumor cells’ self-renewal, viability and migration ability." (PMID 28477008, 2017). "Taken all the data together, we concluded that GLI1 expression is an important factor for maintenance of the putative cancer stem cell population as indicated by tumor sphere forming efficiency and side population." (PMID 28404967, 2017). "On day 30, when all nude mice were sacrificed, the tumor tissues were obtained and underwent immunohistochemistry for Gli1 and MGMT expression." (PMID 29225516, 2017). "Taken together, our studies demonstrate that FoxM1 and Gli1 are aberrantly elevated in CRC tumor tissues." (PMID 28148279, 2017). "The logistic regression also showed that GLI1 by itself has appreciable discriminatory power between normal and tumor tissues (p < 0.001; ROC curve area = 0.7730; 95% CI for the ROC curve (0.6687, 0.8773))." (PMID 28112165, 2017). "GLI1 shRNA expression also reduced the tumor sphere forming efficiency (with the control ∼38 spheres /2000 cells and Gli1 knockdown cells 29 spheres/ 2000 cells, P = 0.032)." (PMID 28404967, 2017). "We correlated the high or low expression of GLI1/GLI3/pathway molecules in the tumor with cancer relapse." (PMID 28413604, 2017). "To assess the discriminatory power of Merlin and GLI1, we applied a logistic regression model to a binary variable of normal and tumor tissue to our data." (PMID 28112165, 2017). "We found that tumor recurrence occurred in 33% of the patients with tumors expressing high levels of GLI1 and the signaling molecules." (PMID 28413604, 2017). "According to previous reports, inhibition of upstream target sonic hedgehog (Shh) results in decreased expression of GLI1, therefore inhibiting tumor growth in xenograft models." (PMID 26988754, 2017). "GLI1 is the nuclear mediator of the Hedgehog pathway that regulates genes essential for various stages of tumor development and progression." (PMID 29190924, 2017). "The primary endpoint was the proportion of patients in each arm who achieved at least a two-fold reduction in GLI1 mRNA expression in post-treatment versus pre-treatment tumor tissue." (PMID 29262631, 2017). "Unlike previous studies using RNA in situ hybridization or questionable antibodies to analyze human tumor samples, the nuclear-localized β-GAL protein (encoded by the lacZ gene) allows the cell type expressing Gli1 to be unambiguously identified." (PMID 27935821, 2017). "Treatment with JQ1, a small-molecule inhibitor targeting BRD4, attenuates mouse BCC cell-derived tumor growth through the suppression of GLI1 and GLI2 transcription." (PMID 29615568, 2017). "Immunohistochemical staining of the tumor tissue demonstrated a significant decrease of Gli1, Shh and Snail expression in the gedunin treated mice compared to the control group." (PMID 26988754, 2017). "Conversely, ectopic expression of GLI1 increased the tumor sphere forming efficiency (with the control ∼32.5 spheres/2000 cells and GLI1 expressing cells 80 spheres/ 2000 cells, P = 0.034)." (PMID 28404967, 2017). "A reduction in the tumor mass is partly explained by the decrease in the expression of GLI-1 and PTCH1 when compared to control groups." (PMID 28948003, 2017). "First, we measured tumor sphere forming efficiency from N87 cells with GLI1 shRNAs, ectopic GLI1 expression or the control cells." (PMID 28404967, 2017). "In LKB1-wild type NSCLCs, the combination of MEK inhibitor and metformin was found to down-regulate GLI1 transcriptional activity to mediate an anti-tumor activity." (PMID 28938614, 2017). "Patched was decreased in 2/3 of the tumor samples, while Gli1 was decreased in all 3 sample s, indicating GDC-0449 downregulated the SHH signaling in vivo." (PMID 29042665, 2017). "According to the proliferation and apoptosis pathways in GSEA, we found GLI1, a well-known transcription factor involved in the growth of many human tumours, was active in patients with higher NOX4 expression." (PMID 28422720, 2017).
tumor (continued). "Previous data suggest that high hedgehog ligand expression in tumor epithelium induces GLI1 (which is indicative of activated hedgehog signaling) in the adjacent stroma, which correlates with invasiveness and poor patient prognosis." (PMID 28275010, 2017). "Overexpression of GLI1 protein has been described in various tumor types such as MB, BCC, RMS, prostate, biliary, breast, lung, colon and bladder cancers." (PMID 28562331, 2017). "Tumours arising from the co-injection of Caov3 SHH-OE cells with CAFs Gli1-shRNA were smaller than those arising from the co-injection of CAFs shNC." (PMID 28978035, 2017). "Gli1 activation is required for tumor cell survival and KRAS-induced transformation in a second pancreatic mouse model." (PMID 29163356, 2017). "The addition of TMZ enhanced the down-regulation of Gli1, and had synergistic inhibitory effect on cell viability, tumor spheroids growth and neurospheres formation." (PMID 28477008, 2017). "mRNA levels of the Hh target genes Gli1 and Ptch1 were markedly reduced in tumor cells from MGCD0103-treated mice, documenting the inhibition of Hh signaling." (PMID 28276480, 2017). "We first monitored the effect of DYRK1B inhibition on tumor-initiating spheroid formation of GLI1-dependent yet SMO-inhibitor resistant PANC-1 cells in 3D cultures." (PMID 26784250, 2016). "Throughout the tumor collection a strong and significant correlation of GLI1 and SHH expression was observed (Spearman r-coefficient 0.8062; p = 0.0065)." (PMID 27109116, 2016). "Suppressing the expression of GLI1 inhibited the overexpression of Bcl-2 and the proliferation of tumour cells while simultaneously promoting cell apoptosis." (PMID 27601167, 2016). "Our present results, combined with preliminary findings from other groups, have provided evidence that high expression of Gal-1 in GC tissues contributes tumor cells migration and invasion via Gli1-driven EMT after binding of Gal-1 to β1 integrin." (PMID 27836001, 2016). "Consistent with the in vitro results, both HL60/RX and HL60/ADR tumor cells exhibited high expression of Gli-1 protein, which was reduced after treatment with LDE225." (PMID 27105509, 2016). "We obtained fresh TNBC tumor tissues after surgery and analyzed these for the expression of Shh, Patched 1(Ptch1), Smoothened (Smo) and Gli1 at the protein level." (PMID 26727947, 2016). "In TNBC, specifically, increased tumor GLI1 expression was found to correlate with higher tumor stage and node‐positive disease." (PMID 27539549, 2016). "Nuclear GLI1 expression was observed in 26/43 (60%) ErbB2-negative tumor samples and 7/8 (88%) ErbB2-positive tumor samples, and the mean percentage of cells with nuclear GLI1 staining was 37 and 55%, respectively." (PMID 26843616, 2016). "Tumours with high CD44, Shh, and Gli1 expression had more cases of advanced tumour invasion, an increased likelihood of lymph node metastasis, advanced TNM stage." (PMID 26839535, 2016). "Gli1 has been proved to be an indispensible gene of Hh signaling and play important roles in types of tumor progressions." (PMID 27863385, 2016). "Our work continues to delineate the interaction between SUFU and GLI1, and specifies which residues are important in the pathogenesis of tumor growth." (PMID 28030567, 2016). "In particular, Gli-1 isoforms lead to tumor invasion and progression, but also play an unclear role in epithelial-mesenchymal transition." (PMID 27918595, 2016). "Contrasting our study, Gan and colleagues described contribution to radioresistance by Gli-1 in an in-vitro tumor model." (PMID 27918595, 2016). "Gli-1 and Gli-2 are able to act as tumor suppressors as well as tumor promoters, implying that both proteins are part of a complex network of various signaling cascades." (PMID 27918595, 2016). "Reduction of tumor size and GLI1 expression in tumor lysates in xenograft mice also showed NQC mediated apoptosis is GLI1dependent." (PMID 26846872, 2016).
tumor (continued). "RNA in situ hybridization (ISH) confirmed that downregulation of stromal Gli1 can occur despite high Ihh expression in the adjacent tumour cells." (PMID 27492255, 2016). "Real-time quantitative PCR confirmed reduced Gli1 expression in tumours from wild-type (wt) mice, with a congruent reduction of the Hh targets, Hhip and Gli2." (PMID 27492255, 2016). "Recently, aberrant expression of Gli1 in tumor cells showed to regulate tumor cell response to replication blocks." (PMID 26988232, 2016). "Correlation analysis revealed that the SHH and GLI1 expression levels significantly correlate on transcript level throughout the tumor collection (Spearman r-coefficient 0.8571; p = 0.0238)." (PMID 27109116, 2016). "Here, we demonstrate the ability of 12 to selectively inhibit the Gli1 mRNA expression and the proliferation of Hh-dependent tumor cells in vitro and in vivo, including MB and BCC, two tumor models where Hh pathway activity occurs by ligand-independent manner." (PMID 27899820, 2016). "In these studies, Gli1 expression has been shown to suppress replication stress in tumor cells by regulating ATR mediated Chk1 phosphorylation through transcriptional regulation of Bid." (PMID 26988232, 2016). "Consistent with this notion mutations at Y147, D159, and H164 have been previously shown to disrupt HH signaling and GLI1 stability, and would be prime candidates to promote tumor growth." (PMID 28030567, 2016). "Sample size didn't influence the relationship between Gli-1 expression and tumor location (n ≤ 70: OR 0.39, 95%CI 0.04-3.44, P = 0.393; n > 70: OR 0.82, 95%CI 0.42-1.61, P = 0.568)." (PMID 27634907, 2016). "Crucially, evaluating the presence of a subpopulation of tumor-propagating cells in patient biopsies identified by GLI1 and NANOG expression had prognostic significance." (PMID 26189795, 2016). "We divided the patients into two groups by the average Gli1 level: low level and high level, and analysed the tumor Gli1 levels with clinical parameters." (PMID 27863385, 2016). "Overexpression of tGLI1 results in larger tumor growth and greater tumor angiogenesis compared to tumors overexpressing GLI1." (PMID 26891329, 2016). "More and more studies found that Foxm1 plays an important role in the occurrence and development of malignant tumors and regulate the tumor progression as a downstream target of Gli1 in cancers like basal cell carcinomas and lung carcinomas." (PMID 27863385, 2016). "The expression of GLI1, Shh and NF-κB correlated with clinico-pathological variables including histological type, tumor grade, tumor size, lymph node metastasis, and EGFR, ErbB2, estrogen receptor (ER) and progesterone receptor (PR) expression." (PMID 26843616, 2016). "Histological analysis revealed Gli1 expression exclusively in the stroma and reduced X-gal staining in the tumours." (PMID 27492255, 2016). "Based on these data, we revisited tumours from Ptch1Col1(het) mice, in which Gli1 expression is increased, and analysed the expression of selected BMP inhibitors using real-time quantitative PCR." (PMID 27492255, 2016). "We observed that only tumor cells expressed GLI1 and NANOG and, importantly, the expression was heterogeneous as seen in cell cultures." (PMID 26189795, 2016). "Most recently, the glioma-associated oncogene homolog 1 (GLI1) has been identified as a TF marker for LNM in PTC and it increases tumor aggressiveness via the Hedgehog signaling pathway." (PMID 27350898, 2016). "The protein level of SHH (ligand) and Gli1 (a transcription factor that can activate the transcription of SHH target genes) were increased in irradiated tumor cells with a peak at 6 Gy." (PMID 25713298, 2015). "We propose that beta-catenin stabilization increases its physical interaction with Gli1, leading to Gli1 degradation and inhibition of Hh signaling, thereby promoting tumor cell senescence and suppression of “tumor take” in mice." (PMID 25645196, 2015).
tumor (continued). "Significant differences were observed in the tumor size and weight between Gli1 silenced and control groups." (PMID 26317501, 2015). "Conditional induction of GLI1 expression in mouse mammary gland induced hyperplastic lesions, defective terminal end buds, and tumor development." (PMID 26633513, 2015). "Similar to CHK1 inhibitors, pharmacological inhibition of aberrantly expressed GLI1 in tumor cells abrogated CPT-induced checkpoint responses, enhanced CPT-induced replication-mediated DNA damage and increased its cytotoxicity." (PMID 26633513, 2015). "In vivo, Gli-1 overexpression correlates with unfavorable overall survival in patients, tumor stage, and lymph node involvement." (PMID 26389956, 2015). "Inhibition of GLI1 not only suppresses tumor growth, but also sensitizes the cancer cells to chemotherapeutic agents." (PMID 26633513, 2015). "Technically there is no discrete “cut-off” for high-Hh or low-Hh expressing GBM in order to stratify patients for therapy with Hh inhibitor drugs, despite the inter-tumor differences in GLI1 expression among the patients varied in 3 orders of magnitude." (PMID 25775002, 2015). "Together these observations suggest an important role for aberrant GLI1 signaling in various stages of tumor development, from inducing mutagenic lesions, carcinogenesis, metastasis and resistance to cancer therapeutics." (PMID 26633513, 2015). "In esophageal cancer, mTOR/S6 kinase signaling was shown to phosphorylate GLI1, promoting its transcriptional activity and tumor growth." (PMID 25749378, 2015). "Together, these data show that ERMS and ARMS cell lines show tumor-intrinsic HH signaling activity as estimated by modulation of GLI1 expression after treatment with SMO – antagonists." (PMID 26106586, 2015). "Apart from the role of GLI1 in directly inducing carcinogenesis, it has been documented that GLI1 has a significant function in inducing tumor recurrence." (PMID 26633513, 2015). "Further analysis of replication stress-induced by DNA topoisomerase 1 (TOP 1) poison CPT revealed aberrant GLI1 important for the activation of S-phase checkpoint mediated by CHK1 in tumor cells." (PMID 26633513, 2015). "Both are capable of interfering with GLI1 and GLI2-mediated transcription and inhibit tumour cell growth in a GLI-dependent manner (Ref." (PMID 25660620, 2015). "In NSCLC specifically, Gli1 has been demonstrated to be elevated in tumor tissue samples and NSCLC cells lines." (PMID 25586417, 2015). "Supplementing the tumor cells with cholecalciferol, a precursor of active vitamin D, blocked the GLI1 activation, inducing cell death and tumor regression in these cells." (PMID 26633513, 2015). "Further analysis revealed that GLI1 binds to the promoter of all five of these genes responsible for cisplatin transport, thus playing a major role in regulating these proteins and tumor resistance to platinum drugs." (PMID 26633513, 2015). "The most promising agent in this context is probably the GLI1/2 inhibitor GANT61 which has been investigated preclinically in numerous tumor types in the last few years." (PMID 26053182, 2015). "The present study revealed a significant increase in SFRP1, SHH and Gli1 expression in irradiated tumor cells." (PMID 25713298, 2015). "There was also elevated mRNA expression of Shh-signaling pathway genes Gli1, Gli2, Gli3 and Ptch1/2 in both tumor-adjacent skin and BCCs of IR-irradiated mice." (PMID 26413810, 2015). "Currently, overexpression of GLI1 has been described in multiple other tumor types such as MB, rhabdomyosarcoma, prostate, biliary, breast, lung, colon and bladder cancer." (PMID 26053182, 2015). "Next, β-catenin level was measured in nuclei, SHH and Gli1 levels were measured in irradiated tumor cells, and the effects of Wnt agonist, Wnt antagonist and β-catenin shRNA on tumor repopulation were investigated." (PMID 25713298, 2015).